CD274 (CD274 molecule)
Diseases named in the same sentence as CD274 in open-access papers (continued):
Sharing a sentence is not in itself a finding about the gene and the disease.
tumor (continued). "Therefore, our data further support the essential role of intrinsic CD274 (PD-L1) and PDCD1LG2 (PD-L2) in maintaining BC’s tumor stem cell phenotype." (PMID 36901916, 2023). "The analyses indicated that cancer types with high KYNU gene expression (>median) generally had elevated gene-based signatures of tumor immune cell infiltrates, including Tregs, as well as immune checkpoint blockade-related genes CD274 (PD-L1), PDCD1 (PD-1), and CTLA4." (PMID 36765792, 2023). "Comparing tumor samples with a desmoplastic growth pattern with non-desmoplastic samples, an increased MFI of CD274 on non-hematopoietic cells within desmoplastic growth pattern tumor samples from CRCLM patients was observed (p < 0.01)." (PMID 37370832, 2023). "The percentage of CD274+ classical, intermediate, and non-classical monocytes was also significantly decreased in tumor samples with a desmoplastic growth pattern (p < 0.05)." (PMID 37370832, 2023). "Moreover, cytokines produced by tumor cells and/or infiltrated immune cells, such as TGF-β, TNF-α, and IFN-γ, induce CD274 gene transcription." (PMID 38038129, 2023). "In addition to FOXP3+ Tregs, marginal tumor regions have more subpopulations with an immunosuppressive phenotype, including CD163+ macrophages, CD11b+ neutrophils, and CD274 (PD-L1)+ tumor cells." (PMID 37529035, 2023). "To test gene induction, we co-transfected them transiently with crRNAs and trans-activating CRISPR RNA (tracrRNA) to induce the transcription of genes commonly expressed by tumor cells (e.g. CD274, NT5E) or genes not expressed by tumor cells such as CD80." (PMID 37732732, 2023). "Finally, to verify the role of RAP2C-AS1 in the tumor immune microenvironment, the relationship between RAP2C-AS1 and immune checkpoint genes (CD274 and CTLA4) was analyzed at the RNA level." (PMID 38071230, 2023). "PD-1 (also known as CD279) is expressed on activated T cells and engages with either of its two ligands (PD-L1, also known as CD274/B7-H1 or PD-L2, also known as CD273/B7-DC) on tumor cells or other immune cells in tumor microenvironment (TME), leading to T cell dysfunction and tumor immune evasion." (PMID 37208329, 2023). "To explore whether A2BR affects NK cell cytotoxicity against tumor cells, we established a CAL27 and NK92 cell co-culture system and treated it with MRS-1706 and/or CD274." (PMID 37663280, 2023). "Within the TME, cDCs have been shown to acquire a common gene program characterized by the expression of immunoregulatory genes (e.g., CD274/PD-L1, PDCD1LG2/PD-L2 and CD200), LAMP3 and CCR7, thus informing the naming of these tumor-specific cells mregDCs or LAMP3+CCR7+ cDCs." (PMID 36949244, 2023). "In addition, the relationship between NOLC1 and CD274, PDCD1, and PDCD1LG2, which are important immune checkpoints for tumor immune escape, was also explored." (PMID 37670166, 2023). "An increased CD274 expression on classical and intermediate monocytes from tumor samples compared to non-tumor samples (p < 0.01 and p < 0.05, respectively) was observed." (PMID 37370832, 2023). "Anti-PDCD1 antibodies only have the ‘Immunostimulant’ effect by activating Teff cells, whereas anti-CD274 mAbs with a functional Fc mediated ADCC directly against tumor cells improve tumor killing without unwanted toxicities." (PMID 37215135, 2023). "In addition, CD274 expression was positively correlated with the stromal score, immune score and ESTIMATE score and inversely correlated with tumor purity." (PMID 36854755, 2023). "We hypothesize that intrinsic expression of CTLA-4, PDCD1 (PD1), CD274 (PD-L1), PDCD1LG2 (PD-L2), CD276 (B7-H3), JAK2, and FoXO1 in neoplastic cells depends on BC immunophenotype, stem cell properties, and tumor microenvironment." (PMID 36901916, 2023). "Furthermore, in most tumor types, immunosuppression-related genes, especially TGFBR1 and PD-L1 (CD274), exhibited a specific correlation with the expression of ORC6." (PMID 36978046, 2023).
tumor (continued). "Finally, we have determined that neoplastic cell-intrinsic CTLA-4, PCDC1 (PD1), CD274 (PD-L1), and PDCD1LG2 (PD-L2) expression is dynamic and varies depending on BC immunophenotype and tumor-immune cell interactions." (PMID 36901916, 2023). "Additionally, CBX2 and CEP55 had a significantly greater impact on tumor patient survival than PDCD1 and CD274." (PMID 37980163, 2023). "This could be because EMT status is correlated not only with pro-tumor conditions (TReg, MDSC, CD274) but also with anti-tumor cells (NK cells and M1 cells), as our results show." (PMID 37884639, 2023). "Our findings showed an increase in the expression of CD274 on classical, intermediate, and non-classical monocytes when comparing tumor with non-tumor samples." (PMID 37370832, 2023). "However, multi-omics analysis for CD274 UTR region, especially circulating tumor DNA (ctDNA), have been little explored in the pan-cancer perspective." (PMID 36717553, 2023). "CD274 (PD-L1) gene expression poorly correlated with LCAM score contrarily to TMB, underscoring the necessity to select better predictive tools that include both tumor intrinsic and immune cell infiltrate features." (PMID 36414693, 2023). "In this model, the IRE1α score predicted CD274 expression (p-value = 0.040), while the PERK score was non-significant (p-value = 0.103), suggesting that activation of CD274 gene expression in tumor-infiltrating macrophages depends primarily on the IRE1α pathway." (PMID 35237269, 2022). "PD-1 has two ligands: PD-L1 (B7-H1 or CD274) and PD-L2 (B7-DC or CD273), which are found on APC, endothelial cells, fibroblasts, and bone marrow-derived mast cells and it can also be expressed by tumor cells." (PMID 36015348, 2022). "The immune checkpoint molecules programmed cell death protein 1 (PD-1, also known as PDCD1) and programmed death-ligand 1 (PD-L1, also known as CD274) are a receptor-ligand system that interconnects in the tumor microenvironment to block anti-tumor immune responses." (PMID 35479647, 2022). "CD274, PDCD1 and CTLA4 are vital immune checkpoints that are responsible for tumor immune escape." (PMID 35637248, 2022). "PD-L1 (also known as CD274 or B7-H1) is a 33 kDa type 1 transmembrane glycoprotein that is widely expressed in macrophages, activated T lymphocytes, B cells, DCs, and also expressed in tumor cells." (PMID 35967444, 2022). "It is widely expressed in tumor-infiltrating lymphocytes (TILs) (70.3%) and interacts with programmed death-ligand 1 (PD-L1, CD274) to induce negative signal transduction of effector T cell activity." (PMID 36005690, 2022). "Furthermore, GILncSig was found to be associated with the upregulation of the expression of immune checkpoints, such as CD274, CTLA4, CD96, and TIM-3, which induced tumor immunotherapy resistance." (PMID 35571034, 2022). "We further revealed that ADAMTS12 expression was positively correlated with immune checkpoint proteins (such as PDCD1, CD274, LAG3, and CTLA4), immunosuppressive genes, chemokines, and chemokine receptors in most tumor types." (PMID 35280819, 2022). "TNFSF9, CD276, CD40, CD274, and CD44 expression was downregulated in cluster 6 (hypoxic tumor)." (PMID 36685583, 2022). "Furthermore, the expression of JMJD6 is mutually exclusive of the tumor immune checkpoints, such as VEGFA, ARG1, EDNRB, IL13, IL12A, CD274 and KIR2DL3 in the majority of cancers, like THYM and HNSC, etc." (PMID 35359945, 2022). "IPCS2/3 subgroups lacked plasmacytoid dendritic cells (DCs) and CD274 (PD-L1), which impeded immune cells to identify tumor cells." (PMID 35935986, 2022). "In addition, the correlation between LOXL2 expression and immune checkpoint markers (CD274, PDCD1, and CTLA-4) suggested a role for LOXL2 in immune regulation of tumor immunity." (PMID 36254230, 2022). "Finally, we saw a significant high expression of immune checkpoint markers PDL1/Cd274 in DCIS macrophages and PD1/Pdcd1 in DCIS T cells, both of which drop in the Tumor state." (PMID 35851387, 2022).
tumor (continued). "IFNΓ is highly expressed in cells of the tumor tissues, and, through phosphorated STAT 1, it binds to a unique IRF-binding sequence element in vitro and chromatin in vivo in the cd274 promoter to activate PD-L1 transcription." (PMID 35628647, 2022). "Finally, the enrichment analysis suggested that CD274 and PDCD1LG2 were not only involved in pan-cancer immunomodulatory regulation but also contributed to tumor metastasis." (PMID 36276934, 2022). "Interestingly, OSCC with high F3 expressed higher levels of the key immune checkpoint molecules CD274/PD-L1, PDCD1LG2/PD-L2 and CD80, especially in tumor dendritic cells." (PMID 35053621, 2022). "The signaling pathway of programmed cell death ligand 1 (PD-L1, B7-H1, or CD274) and its receptor PD-1 (CD279) is an important mechanism tumors use to escape antitumor immune responses and maintain an immunosuppressive state in the tumor environment." (PMID 35917184, 2022). "Immune checkpoints (ICs) generally refer to key inhibitory factors of the immune system, including programmed cell death 1 (PD-1 or CD279) and its ligand programmed cell death 1 ligand 1 (PD-L1 or CD274) that control the T cell response and fate during tumor immunity." (PMID 36741695, 2022). "In addition, Programmed death ligand 1 (PD-L1, CD274), expressed on tumor and/or immune cells in the TME, interacts with PD-1 on tumor-infiltrating lymphocytes, attenuating effector T-cell responses and allowing tumors to escape immune attack." (PMID 35651807, 2022). "Intriguingly, together with CD274 (PD-L1), CD276 (B7-H3) and VEGFA were both highly expressed in the cold tumours, which could be further investigated as novel immunotherapy targets for such patients." (PMID 36267973, 2022). "PD-L1, also known as CD274, binds to PD1 receptor to block tumor-infiltrating lymphocytes." (PMID 35466317, 2022). "PD-1 (also called PDCD1, CD279) is expressed on immune cells, especially tumor specific T cells, while PD-1 ligand PD-L1 (also called B7-H1, CD274) is expressed on tumor cells as an “adaptive immune mechanism” to escape anti-tumor response (Han, Liu & Li, 2020)." (PMID 34458019, 2021). "We found that CD274 and CTLA4 show significantly higher expression in the TNFSF10high group than in the TNFSF10low group; however, PD-L1 (CD274) was predominantly expressed by tumors while CTLA4 and LAG3 were mostly expressed by T cells in the tumor microenvironment." (PMID 34167551, 2021). "Concerning prototypical immune checkpoints, expression of CD274 (PDL1) and PDCD1LG2 (PDL2), which encode ligands for PDCD1 (PD1), expressed in tumor-infiltrating T cells, was virtually absent in the profiled human GBM tumors." (PMID 34917090, 2021). "Moreover, it is generally accepted that the high expression of immune checkpoints such as CTLA4, PD-1, BTLA, CD274, and LAG3 will benefit tumor cells to escape immune surveillance, avoid immune-mediated apoptosis, and finally lead to poor prognosis." (PMID 34745259, 2021). "We found different tumor purities, immune scores, stromal scores, fractions of different immune cells, expression of several HLA genes and expression of five immune checkpoint molecules (CTLA4, CD274, HAVCR2, LAG3 and TIGHT) among UCEC subtypes." (PMID 34368124, 2021). "We show that high expression of PD-L1 in tumor cells is due to high level CD274 focal amplification without lymphocyte infiltration." (PMID 33479394, 2021). "Immune checkpoints such as PD-L1/CD274 and CTLA4 are often overexpressed in tumor cells to devitalize effector T cells and suppress immune responses, which could be targets for immunotherapy." (PMID 33928021, 2021). "High CD274 expression was found in tumor tissues (T3) with BRD4-S expression but without BRD4-L expression." (PMID 34326687, 2021). "The tumor tissues had elevated levels of CMTM6, CMTM4, and CD274 (PD-L1) transcripts." (PMID 34680324, 2021).
tumor (continued). "The tumor suppression potential of GRWD1 in KRIC and its correlation with MSI and the CD274 gene may be significant for the therapy of KRIC." (PMID 34616846, 2021). "Using TISIDE (an integrated repository portal for tumor-immune system interaction) platform, we observed a significant reverse correlation (Spearman r = −0.503, p < 2.2 × 10−16) between RKIP and CD274 (PD-L1) expression in PC (n = 498, TCGA PC dataset)." (PMID 34945007, 2021). "Furthermore, PD-1 ligand 1 molecule (PD-L1, also known as B7-H1 or CD274) has been described on APCs and tumor cells to induce cell death and promote iTreg cell conversion through the binding of PD-1 expressed on activated CD4+ T cells." (PMID 33901179, 2021). "Tumour next-generation sequencing showed a high TMB and a CD274 (PD-L1) amplification." (PMID 34824629, 2021). "Also, deletions of JAK2, CD274 and MYD88 genes, and amplification of FGFR4 and NPM1 genes, are also involved in clinical trials for other tumor types." (PMID 33668731, 2021). "As expected from our immunohistochemical analysis, the CD274 gene coding for PD-L1 arose as the most significantly upregulated gene in the PH group accounting mostly for the tumor PD-L1 expression, not for the infiltrating immune cells (green writing)." (PMID 34572789, 2021). "Consistent with previous reports describing tumor-derived EVs, immune checkpoints CD47 and CD274/PD-L1, and key regulators of myeloid differentiation (e.g., TRIB1, SOCS3, STAT3) were upregulated in EwS EV-treated cells compared to control, with TC32 EVs generally eliciting stronger effect." (PMID 34440851, 2021). "We found that tumor-infiltrating CD33high cells showed high gene expression levels of CD36, CD14, FUT4 (CD15), CD80, CD86, CSF1R and immune checkpoint ligand genes including CD274 (PD-L1), LGALS9 (galectin-9), PVR and VSIR." (PMID 33000418, 2021). "HDAC inhibition could downregulate AR protein levels and significantly induce PD-L1 expression by increasing the acetylation of the CD274 promoter, resulting in an immune-evasive microenvironment for tumor progression." (PMID 34830196, 2021). "In this disease model, Siglec-15 functions as a “ligand” for an unknown inhibitory receptor on cytotoxic T cells, where it acts in a similar manner as PD-L1 (B7-H1, CD274) on tumor cells or tumor stroma involving immune checkpoint molecule PD-1 on T cells." (PMID 34988324, 2021). "In the meantime, the elevated expression of ICGs such as PDCD1, CD274, CTLA4 may also modulate tumor response to immunotherapy." (PMID 35116021, 2021). "PD-L1, also known as CD274 or B7-H1, is a transmembrane protein physiologically expressed on the plasma membrane of antigen presenting cells and aberrantly expressed by tumor cells, supporting tumor immune evasion." (PMID 34572014, 2021). "This consisted of elevated levels of CD274 expression, and elevated IFN, TNF, and the “up” PD-L1CON scores (normalised to matched pre-treatment tumours from the same patient), while oxidative phosphorylation, down PD-L1CON, and differentiation scores were reduced." (PMID 34503064, 2021). "The enrichment trend of CD274 and POLE alterations in high PD-L1 group may be the reason for the immune-active status of the tumor." (PMID 35145511, 2021). "Half of the CA-CRCs (16/31, 52%) expressed CD274-positive immune cells, whereas tumor cells were CD274-negative." (PMID 34680073, 2021). "Moreover, we found that GSK591 treatment not only inhibited tumor cell survival but also induced tumor cell expression of type 1 IFN response and CD274 genes, which activated the PD1/PD-L1 axis and eliminated T cell antitumor activity." (PMID 35111150, 2021). "In addition, we found that CD274 and PDCD1LG2 were correlated with gene markers in tumor-infiltrating immune cells." (PMID 33833994, 2021). "Moreover, CDCA7 was significantly correlated with tumor-related immunosuppressive molecules including PDCD1, CD274, CTLA4, BTLA and LAG3." (PMID 33648519, 2021).
tumor (continued). "The result showed that NXA1 expression was positively correlated with CD274 and CD276 expression, which indicated ANXA1 could influenced the tumor microenvironment by regulating these tumor immune genes." (PMID 34422796, 2021). "As TNC impacted expression of Cd274, we investigated gene expression with inhibitors as described and found that Cd274 was reduced in the tumor cells with the TLR4 inhibitor Cli95 yet not with the other inhibitors (Fig EV5F)." (PMID 33988305, 2021). "Rather than assessing only the PD-L1/CD274 expression of tumor cells, the additional monitoring of PD-L1/CD274 expression of immune cells in the blood appears to be mandatory for predicting therapy responses in patients undergoing checkpoint blockade therapy." (PMID 33066260, 2020). "Programmed death ligand 1 (PD-L1), also known as B7-H1 or CD274, is expressed on the activated T cells, B cells, macrophages, tumor cells, interstitial cells, and vascular endothelial cells (ECs), PD-L1 regulates inflammation in the heart, liver, placenta, cornea, retina, and etc." (PMID 32631356, 2020). "Interferon-gamma produced by activated T cells binds to its receptor on tumor cells and determines STAT1 activation and transcription of IRF1/7 which in turn binds to the CD274 promoter, increases PD-L1 transcription and, ultimately, the expression on tumor cells." (PMID 33114576, 2020). "Besides, CD274, CD8A, GZMA, and PRF1 were positively correlated with the stromal score or immune score in almost all 33 tumor types." (PMID 33585244, 2020). "In this disease model, Siglec-15 plays a role as a “ligand” for an unknown inhibitory receptor on cytotoxic T cells, in much the same way as PD-L1 (aka B7-H1, CD274) on cancer cells or tumor stroma engages immune checkpoint molecule PD-1 on T cells." (PMID 31900164, 2020). "RNA-seq data also showed that THZ1 could diminish transcripts of MYC-targeted genes, such as HK2, CDC25A, GLUT1 (SLC2A1), PD-L1 (CD274), BRCA1, and BRCA2, which are important mediators of MYC’s function in tumor metabolism, immune evasion, and DNA repair." (PMID 32690037, 2020). "However, immune checkpoint genes including IDO1, HAVCR2, PDCD1LG2, CD274, CTLA4, and TIGIT were significantly up-regulated in tumor samples (fold change >1.30, FDR q ≤ 1.0e-5)." (PMID 33257699, 2020). "In fact, CXCR4, SPP1, ACKR3, CCL2, PTGS2, CD274 (PD-L1), CXCL11 were upregulated while CCL28, CCR1, CCR7 were down regulated in both comparisons (blue boxes), suggesting this as a signature specific of the core region of the tumor." (PMID 33066172, 2020). "CD80 has been shown to interact with PD-L1/CD274 in cis on antigen-presenting cells to disrupt PD-L1/PD1 binding, and CD80 expression might differ between antigen-presenting cells in blood and tumor tissue." (PMID 33066260, 2020). "Our results are in contrast to data from murine tumor models, where PD-L1/CD274-expressing antigen-presenting cells, rather than tumor cells, demonstrated essential antitumor effects of anti-PD-L1 monotherapy." (PMID 33066260, 2020). "These ligands, PD-L1 (CD274 or B7H1) and PD-L2 (CD273), were found expressed in some tumor cells." (PMID 31303863, 2019). "Further, tumor cells promote T cell dysfunction through expression of ligands for inhibitory receptors, as, for instance, programmed cell death ligand 1 (CD274, best known as PD-L1)." (PMID 31535086, 2019). "Moreover, enhancers of migration and angiogenesis such as GPNMB, PTGS2, CD274, and ZNF703 were significantly downregulated suggesting suppression of tumor malignancy." (PMID 31842391, 2019). "Surprisingly, there were no obvious tumor nodules in the anti-CD47 or anti-CD274 group compared with other control groups." (PMID 30872703, 2019). "The first and the best characterized strategy used in clinics is based on the inhibition of the interaction of programmed cell death 1 (PD1) present on the surface of T lymphocytes with its ligands PD-L1/CD274 and PD-L2/PDCD1LG2 expressed by tumor cells and antigen presenting cells." (PMID 31467175, 2019).